CDK2 (cyclin dependent kinase 2)
Diseases named in the same sentence as CDK2 in open-access papers (continued):
Sharing a sentence is not in itself a finding about the gene and the disease.
breast cancer (continued). "The continuous advancement of these investigational drugs reinforces the therapeutic relevance of CDK2 and propels the development of next-generation targeted small-molecule therapies for resistant breast cancer." (PMID 40949156, 2025). "In cluster 2, which is enriched for ER+ and/or HER2+ breast cancer and Ewing sarcoma, many cell lines that were sensitive to CDK4 loss were less affected by CDK2 depletion, suggesting a reciprocal relationship in the requirements of these kinases." (PMID 39924553, 2025). "Using drugs that inhibit enzymes called CDK4/6 and CDK2 extends the G1 phase of the cell cycle and helps to slow the growth of drug-resistant breast cancer." (PMID 41410553, 2025). "A stem-like subpopulation of inflammatory breast cancer cells exhibits CDK-2–cycling E complex overexpression, which renders the cells chemotherapy-resistant." (PMID 38184514, 2024). "Continuous treatment of a CDK2 inhibitor delayed the development of cyclin E-induced mammary tumour progression in that study." (PMID 38732271, 2024). "To determine the impact of selective CDK2 inhibition with INX-315 on the transcriptome of CDK4/6i–resistant breast cancer, we treated abemaciclib and abemaciclib/fulvestrant–resistant cells with INX-315 and performed RNA-sequencing." (PMID 38047585, 2024). "Of particular importance will be the development of CDK2 + CDK4/6i combinations in the treatment of breast cancer." (PMID 38047585, 2024). "These interactions contributed to the binding affinity with CDK2, emphasizing its capacity as a therapeutic agent for the treatment of breast cancer." (PMID 39404419, 2024). "We ascertained EGFR expression and cyclin A, cyclin E, and CDK2 levels in breast cancers by bulk, single-cell, and spatial transcriptomic analyses." (PMID 38772416, 2024). "PTENP1 also contributes to intra-S to G2/M phase arrest by targeting CDK2-cyclin A2 in breast cancer cells, suggesting its relevance in cell cycle regulation." (PMID 39125832, 2024). "Inhibition of the NFKB (NRF) TF along with non-coding the RNA TROJAN has been shown to abolish CDK2 activity and reverse the resistances of breast cancer cells to CDK4/6 inhibitors." (PMID 39376611, 2024). "Another study found high expression of TROJAN in ER+ breast cancer, which by inhibiting cyclin-dependent kinase 2(CDK2) activity, reversed resistance to CDK4/6 inhibitors." (PMID 39253075, 2024). "Anomalous activation of CDK2 has been recognized as a primary mechanism of resistance to CDK4/6 inhibition in hormone-receptor-positive (HR+) breast cancer." (PMID 39404419, 2024). "Second, we have found that although CDK4/6i monotherapy is sufficient to induce complete cell cycle arrest in breast cancer cells, their combination with CDK2 inhibitors upfront significantly delays the development of acquired resistance." (PMID 38047585, 2024). "Phosphorylation of downstream KAT7 by the LMW-E/CDK2 complex enhances the self-renewal ability of breast cancer cells and the enrichment of cancer stem cells populations." (PMID 36724120, 2023). "In conclusion, combination of molecular docking and molecular mechanics as well as molecular dynamic simulations, we recognized inhibitors potent for CDK-2 protein in treating estrogen receptor positive breast cancer." (PMID 37925393, 2023). "Phosphorylation of EZH2 at T435 and T487 by CDK1 and CDK2 epigenetically silences target genes in breast cancers." (PMID 37803297, 2023). "KAT7 has recently been reported to function as a novel cyclin E/CDK2 substrate that enriches stem-like cells in breast cancer." (PMID 36724120, 2023). "Meanwhile, CDK2-mediated EZH2 phosphorylation(pT416) drives tumorigenesis— converts the luminal breast cancer to TNBC." (PMID 37803297, 2023).
breast cancer (continued). "More importantly, we revealed that high MITH indicated cell cycle pathway activation in HR+ breast cancers and such activation was mainly due to the upregulation of Cyclin E/CDK2, which was an important mechanism of CDK4/6 inhibitor resistance." (PMID 37880211, 2023). "To offer a glimpse into future clinical applications, we analyzed the gene expression of Pal targeted genes, CDK4 and CDK6, and Nif targeted genes STAT3 and CDK2 in breast cancer through the TNMplot database." (PMID 37752122, 2023). "Previous studies have reported echinacoside to reduce the expression of cyclin D1 in breast cancer cells, but this is the first study to demonstrate its ability to reduce the expression of CDK2." (PMID 37822691, 2023). "Previous research has discovered that ZEB1 promotes breast cancer cell proliferation by down-regulating p21 and up-regulating CDK2 and CDK4 through the cell cycle." (PMID 37978168, 2023). "First, we overexpressed CDK2/cyclin E by means of adenovirus in MDA MB 468 cells (breast cancer cells with bi-allelic RB deletion)." (PMID 36778475, 2023). "Overexpression of circNCOR1 reduced breast cancer radiosensitivity to promote breast cancer growth by acting as a decoy of hsa-miR-638 to regulate the level of CDK2." (PMID 38186573, 2023). "Currently, CDK2 is considered a potential target for therapy in breast cancer, and more selective CDK2 inhibitors are in preclinical development." (PMID 37509331, 2023). "The major goal of this study was to identify the potential inhibitors of CDK-2 present in Moringa oleifera for treating hormonal receptor positive breast cancers." (PMID 37925393, 2023). "By using this approach of computational or in-silico drug design we determined the anticancer potential of Moringa oleifera in ER + breast cancer targeting CDK-2 enzyme & evaluated our results using Maestro v13.2, Schrödinger." (PMID 37925393, 2023). "Breast cancer cells with higher RNF126 expression have CDK2-mediated replication stress, which makes them potential targets for ATR inhibitors." (PMID 36539893, 2022). "Therapeutic resistance of HER2+ breast cancer has been linked to cyclin D1-CDK4/6-mediated RB phosphorylation and also the overexpression of cyclin E and increased CDK2 activity." (PMID 36466034, 2022). "It has been suggested that CDK2 inhibition would target the reliance of poor prognosis breast cancers, including TNBCs, on cyclin E/CDK2 activation." (PMID 35884422, 2022). "While clinical studies have focused predominantly on the use of CDK4/6 inhibitors to treat endocrine-resistant breast cancer, and use of CDK2/1 inhibitors has also been considered." (PMID 35441158, 2022). "In xenogaft models of breast cancer, depletion of CDK2 and CDK4/6 has reduced tumor growth and palbociclib resistance." (PMID 36266723, 2022). "Herein, we show that upregulation of CDK6, p-CDK2, and/or cyclin E1 is associated with adaptation and resistance to AI-monotherapy and combined CDK4/6i and ET in ER+ advanced breast cancer." (PMID 36153348, 2022). "The newly synthesised hybrids were then tested for their CDK2 inhibitory activity and cytotoxic activity using pancreatic cancer (Panc-1), breast cancer (MCF-7), and lung carcinoma (A549) cell lines." (PMID 35470754, 2022). "Our analyses also confirmed previous findings that the high expression of cyclin E and CDK2 correlated with a worse overall survival in breast cancers." (PMID 35884422, 2022). "Blocking p27-Y88 phosphorylation by Brk-SH3 peptide efficiently inhibited CDK4 and CDK2 activity and arrested proliferation of breast cancer cells in a xenograft model." (PMID 35597806, 2022). "RNF126-expressing breast cancer cells exhibit CDK2-mediated replication stress that makes them potential targets for ATR inhibitors." (PMID 36539893, 2022).
breast cancer (continued). "Mechanistically, there were confirmed binding sites between hsa_circ_0006014 and miR-885-3p, and hsa_circ_0006014 promoted breast cancer cell proliferation partially by sponging miR-885-3p and influenced CDK2/CCNE1 and CDK4/6/CCND1." (PMID 35383130, 2022). "In breast cancer, up-regulation of MTHFD2, which contributes in the cell cycle through binding to CDK2, has been associated with shorter OS, tumor grade and stage." (PMID 36266723, 2022). "Cyclin-dependent kinase 2 (CDK2) was involved in regulating replication stress in breast cancer cells with intact RNF126." (PMID 36539893, 2022). "The downregulation of TROJAN suppressed breast cancer cell proliferation in vitro and tumor growth in vivo by regulating cyclin-dependent kinase 2 (CDK2)." (PMID 36613528, 2022). "In line with previous studies, our analysis of clinical data revealed that CDK2/CDK4 are overexpressed in breast cancer patients and contribute to tumor progression, metastasis, invasive phenotypes and non-responsiveness to chemotherapy." (PMID 34421361, 2021). "The rationale to target CDK2 for treatment of malignancies includes the indispensable role of CDK2 in proliferation and overexpression of its binding partners, cyclin A or E in several cancers, such as ovary cancer, breast cancer and glioma etc.." (PMID 33803751, 2021). "In an analysis of global gene expressions, increased expression of CDK2 was found in the palbociclib-resistant breast cancer cell lines." (PMID 34123801, 2021). "As expected, the higher expression profiles of CDK2 and CDK4 were associated with high risk scores and shorter survival periods of the breast cancer cohorts." (PMID 34421361, 2021). "CDK2 inhibition has been found to sensitize tamoxifen resistant breast cancer cells both in vitro and in vivo." (PMID 33805800, 2021). "In the present study three series of oxindole-benzofuran hybrids were designed and synthesised as dual CDK2/GSK-3β inhibitors targeting breast cancer (5a-g, 7a-h, and 13a-b)." (PMID 33327806, 2021). "Another study has shown that loss of PTEN mediates overexpression of activated AKT, CDK4, and CDK2 in CDK4/6i-resistant breast cancer cell models." (PMID 34771560, 2021). "The target benzofuran–indolinone conjugates were developed as dual inhibitors for the two key oncotargets CDK2/GSK-3β that are involved in breast cancer." (PMID 34946704, 2021). "In particular, CDK2 inhibition was found to effectively hinder breast cancer cells proliferation including those resistant to hormonal therapy." (PMID 33327806, 2021). "Our findings lend credence to this proposition as we establish CDK2 as the primary effector of MAPK in HER2-inhibitor-resistant breast cancer cells." (PMID 34795269, 2021). "Accumulating evidence suggest that CDK2 inhibition are particularly useful for several cancers including lung cancer, prostate cancer, and breast cancer." (PMID 33686022, 2021). "Different indole and indole isosteres-based compounds were shown to potently inhibit cyclin-dependent kinase 2 (CDK2) activity as part of a G1 cell cycle arrest of human breast cancer cells." (PMID 33466812, 2021). "In another study, it was reported that treatment of MCF-7 breast cancer cell line with 1,25(OH)2D3 induces cell cycle arrest at G0/G1phase via inhibition of CDK2 and CDK4 56-60." (PMID 34421361, 2021). "Several lung cancer, diffuse large B-cell melanoma, and lymphoma cases have reported CDK1 overexpression, while CDK2 overexpression has been observed in breast cancer, laryngeal squamous cell cancer, colorectal carcinomas, and melanomas." (PMID 34361615, 2021). "Hyperactivation of CDK2 is correlated with cyclins A and E overexpression and/or amplification in human cancers, particularly lung, thyroid, ovarian, endometrial, and breast carcinoma, osteosarcoma, and melanoma." (PMID 34361615, 2021).
breast cancer (continued). "In conclusion, our study indicated that estrogen-responsive lncRNA MAFG-AS1 up-regulated CDK2 by sponging miR-339-5p, which promoted ER+ breast cancer proliferation." (PMID 33098638, 2020). "TROJAN/NKRF increases cyclin-dependent kinase 2 (CDK2) expression to promote proliferation of Estrogen receptor positive (ER+) breast cancer via the G1/S phase transition." (PMID 33050646, 2020). "We concluded that miR-339-5p inhibited the proliferation of breast cancer by targeting and inhibiting CDK2." (PMID 33098638, 2020). "We have found total 22 compounds capable of inhibiting CDK2 in luminal A breast cancer models in vitro with inhibitory effects on cell viability and/or motility." (PMID 32947901, 2020). "Four kinases-serine/threonine-protein kinase Nek2 (NEK2), aurora kinase A (AURKA), cyclin-dependent kinase 1 and 2 (CDK1 and CDK2) were the predicted to be activated across breast cancer, colon cancer, LUAD, ovarian cancer, and UCEC." (PMID 32033228, 2020). "SA inhibited the cell cycle at the G1 and G2 phases, increased cell cycle inhibitor p21CIP1/WAF1 and p27KIP1 levels, and decreased cyclin-dependent kinase 2 (CDK2) phosphorylation in Hs578T human breast cancer cells." (PMID 32526973, 2020). "We noticed that CDK2 has been reported to be up-regulated and promote the progression of breast cancer and so was selected as a target gene." (PMID 33098638, 2020). "The cyclin E/CDK2 complex phosphorylates KAT7 at Thr88 which promotes the enrichment of breast cancer stem-like cells." (PMID 33014433, 2020). "In sensitive breast cancer cell lines ATRA can down-regulate the expression of some anti-apoptotic molecules as Bcl-2, cdk2, cyclin D1, and survivin, that are overexpressed in one third of breast cancer types." (PMID 32012980, 2020). "To validate, we found CDK2 protein level was higher in breast cancer cells than normal breast cells." (PMID 31892853, 2020). "For instance, NF-κB was reported to trigger cyclin D1 expression in breast carcinoma cells and was found to interact with cyclin-dependent kinase 2 (CDK2) and cyclin E complex in lymphocytes." (PMID 33375283, 2020). "Other notable genes decreased by SK1 KD were NDUFA2 in prostate and E2F5, NAGK, VAPB, NFATC3, CDK2 in breast cancer cell lines." (PMID 30971929, 2019). "Overexpression of the cyclin E1/CDK2 complex also has been reported in immortalized rat embryo fibroblasts and breast cancer cells." (PMID 30634632, 2019). "Overall, we inferred that breast cancer with low p21 expression largely depends on the CDK2–cyclin E complex to progress to the S-phase; thus, CDK4 and CDK6–cyclin D complex are no longer necessary to overcome the G1–S checkpoint." (PMID 31448056, 2019). "TNBC cell lines BT549, Hs578T, and SUM-149 breast cancer cells treated with dinaciclib also exhibited upregulation of ERα expression and reduction of phospho-CDK2 and pT416-EZH2." (PMID 31704972, 2019). "For example, miR-765 reportedly targets the CDK2 gene, and inhibits cell migration and tube formation in osteosarcoma cells, and cell proliferation, migration, and invasion in breast carcinoma cells." (PMID 31261874, 2019). "Abnormal expression of CDK2 was found in breast cancer, gastric cancer, colon cancer, and prostate cancer, which was closely related to the development of these tumors." (PMID 29482572, 2018).
breast cancer (continued). "To confirm this finding, we investigated the gene expression levels of TAP and CDK2 during PS exposure in breast cancer cells using Q-PCR." (PMID 29435127, 2018). "CCNE1-amplified breast cancer cells were sensitive to CDK2 inhibitors, resulting in reduced cancer cell survival." (PMID 27582547, 2017). "We therefore measured changes in CDK2 and CDK4 expression in both HR-NB and breast cancer because CDK2 is a marker of ESCs, whereas CDK4 is a marker of adult stem cells." (PMID 28246384, 2017). "The known interaction of CDK2 and Cyclin E1 was examined and positive foci were observed in both the nucleus and cytoplasm of T47D breast cancer cells." (PMID 29146920, 2017). "Another pathway involving cyclin E/CDK2 also contributes to cell cycle progression in breast cancer cells." (PMID 28152041, 2017). "Because CDK2 is involved in a variety of cancers, such as breast cancer, NSCLC, and CRC, it is conceivable that circ-Foxo3 takes a part in cancers above by formation of circ-Foxo3-p21-CDK2 ternary complex." (PMID 28049499, 2017). "An in vitro study using several breast cancer cell lines has shown that down-regulation of CDK2 after treatment with erlotinib was correlated with a reduction of cell viability." (PMID 27655662, 2016). "CDK2, like the targets of the recently approved breast cancer drug Ibrance, is a member of the cyclin-dependent kinase family of Ser/Thr protein kinases whose de-regulation occurs frequently in certain types of cancer." (PMID 27296290, 2016). "InuA upregulated the expression of p21 and Bax, induced the cleavage of PARP, and reduced the expression of Cdk2, Cdk4, Cdk6, Cyclin D1, Cyclin E, c-Myc, and Bcl2 in both breast cancer cell lines." (PMID 27105525, 2016). "CDK2 overexpression has been reported in laryngeal squamous cell cancer, advanced melanoma and breast cancer." (PMID 25625291, 2015). "In MCF7 breast cancer cell lines, cyclin dependent kinase 2 (CDK2) and CDK4 were reported to be inhibited by 30 μM EGCG." (PMID 25025898, 2014). "The expression of CDK2 and CyclinD1 changed accordingly after downregulation or upregulation of CDK2-AP1 by western blot, suggesting a role of the CDK2-AP1/CDK2/CyclinD1 cell cycle pathway in the initiation and progression of breast cancer." (PMID 25550687, 2014). "We have followed the expression of CDK2-AP1 and its related molecules (CDK2 and CyclinD1) in normal human breast tissues and breast cancers at different stages." (PMID 25550687, 2014). "Many of the genes in the RRHGE gene signature are already defined as well-known oncogenes, such as AR, BRCA1, CDK2, and CCND1, besides others, whose differential expression has been associated with the subtypes of breast cancer." (PMID 24563630, 2014). "Some SNPs in DNA repair related genes, such as APE1, XRCC1, ERCC1 and XPF were found to be associated with breast cancer susceptibility in Chinese Han population, so did some SNPs in cell-cycle genes such as CCNE1 and CDK2." (PMID 24386390, 2013). "Rather, we propose that a dual treatment strategy targeting CCND1/CDK4 and CCND1/CDK2 complexes will be necessary to effectively treat luminal breast cancers arising from elevated CCND1." (PMID 23390492, 2013). "Further studies will be done to clarify the PI3K signaling cascade in CDK2/ERalpha regulation in breast cancer." (PMID 23390529, 2013). "Overall, our results suggest a new pathway that involves PI3K/AKT, CDK2 and Pin1 and open up new opportunities for treating ERalpha-positive breast cancer patients who are resistant to hormonal therapy." (PMID 23390529, 2013). "The results presented in this report clearly show that Cdk4 is more influential than Cdk2 in mediating CA in Her2+ breast cancer cells." (PMID 23776583, 2013).